EIF4EBP1 (eukaryotic translation initiation factor 4E binding protein 1)
Diseases named in the same sentence as EIF4EBP1 in open-access papers (continued):
Sharing a sentence is not in itself a finding about the gene and the disease.
tumor (continued). "In the purple module, we found Eif4ebp1 with reduced expression in tumor." (PMID 28212608, 2017). "Furthermore, patients whose tumours exhibited EIF4EBP1 expression alteration had significantly poorer disease-free survival (P = 0.042) and overall survival (P < 0.001)." (PMID 26646586, 2016). "EIF4EBP1 protein expression in HCC tissues is significantly correlated with serum AFP (P = 0.003) and marginally significantly associated with pathological grade (P = 0.085), tumor number (P = 0.084), tumor embolus (P = 0.084) and capsulation (P = 0.073)." (PMID 25658620, 2015). "Phosphorylated EIF4EBP1 is thought to be an indicator of tumorigenic activity and is associated with poor survival in cancer patients, while nonphosphorylated EIF4EBP1 acts as a tumor suppressor." (PMID 33968297, 2021). "Moreover, miR-125a and miR-125b downregulates VEGF and EIF4EBP1 levels, suggesting that suppression of these tumorigenic targets may be the mechanism by which these miRNAs suppress tumour growth." (PMID 26646586, 2016). "Immunohistochemical database analysis reveals that EIF4EBP1, RIMKLA, and BIRC5 are highly expressed in tumour tissues, while the PCK1, PLG, PEBP1, and CAT show a lower expression in tumour samples." (PMID 40591061, 2025). "The results revealed that EIF4EBP1, RIMKLA, and BIRC5 upregulated in tumor tissues, while other genes downregulated in normal tissues, which is consistent with the results in TCGA-KIRC datasets." (PMID 40591061, 2025). "TalaA downregulated the phosphorylation of a series of transcription factors, including JUN, NFATC1, EIF4EBP1, ABL, RPS6KB1, and EIF4ENIF1, most of which play pivotal roles in cell proliferation and tumor progression." (PMID 37866481, 2023). "We found that TGFA, SHC1, PIK3CD, GAB1, and AKT3 were negatively correlated with six tumor immune cells in KIRC, and EIF4EBP1 was positively correlated with macrophage infiltration." (PMID 35903358, 2022). "The expression levels of EIF4EBP1 and BCL2A1 in BC patients are significantly higher than those in normal breast tissues, and with the increase of tumor malignancy." (PMID 36524001, 2022). "We found that BP can repress the mTOR pathway by downregulating MLST8 and EIF4EBP1 to inhibit AML cell proliferation and in vivo tumor growth." (PMID 35579750, 2022). "Overexpression of EIF4EBP1 has been found in various carcinomas (brain, CNS, CRC, kidney and other cancer types), and EIF4EBP1 acted as a hypoxia-inducible switch to promote tumor angiogenesis, survival in advanced cancer." (PMID 34136395, 2021). "EIF4EBP1 (4E-BP1) is an important downstream target of mTOR and controls the mRNA translation of many tumor progression-related genes." (PMID 34953500, 2021). "These inhibitors attenuated tumor growth, with AZD2014 exerting the most significant effects and also reduced mTORC1 activation (as assessed by EIF4EBP1 phosphorylation) and the expression of EZH2 and SUZ12 proteins." (PMID 31263101, 2019). "Therefore, EIF4EBP1 protein may not only act as a tumor suppressor but also as an oncogene." (PMID 25658620, 2015). "Once activated, mTORC1 phosphorylates its effector 70kDa ribosomal protein S6 kinase (p70S6K) and eukaryotic translation initiation factor 4E-binding protein 1 (4E-BP1), thereby initiating processes such as transcription, proliferation, growth, and protein synthesis in tumor cells." (PMID 38672455, 2024). "To test dependence of EIF4EBP1 expression as prognostic factor on established factors of poor prognosis, we performed multivariate analysis to determine the statistical interaction between high EIF4EBP1 expression and MYCN amplification status, tumor stage or age at diagnosis." (PMID 35379801, 2022). "This was not independent of MYCN amplification status, tumor stage or age at diagnosis, which can be explained in part by the regulation of EIF4EBP1 promoter by MYCN which we characterized." (PMID 35379801, 2022).
tumor (continued). "Furthermore, four genes (MAP2K1, EIF4EBP1, MAPK8, and RPS6KB1) were enriched in ERBB signaling pathway, required for GBM stem cell proliferation, and three genes (MAP2K1, MAPK8, and RPS6KB1) were enriched in NFAT pathway, promoting tumor angiogenesis." (PMID 28056026, 2017). "Similarly, EIF4EBP1, as the repressor of EIF4E, also may act as tumor promoter or tumor inhibitor." (PMID 25658620, 2015).
cancer (290 papers, 2009 to 2026). A tumor composed of atypical neoplastic, often pleomorphic cells that invade other tissues. "In particular, MYC and ATF4 have been shown to co-regulate EIF4EBP1 transcription in cancer cells, providing one potential mechanism underlying EIF4EBP1 overexpression in cancer." (PMID 35228525, 2022). "Additionally, consistent with previously published data, chr8 gain and high EIF4EBP1 expression are associated with unfavorable patient survival in several other cancer entities (chr8 gain in 4 and high EIF4EBP1 expression in 14 of 32 identified entities)." (PMID 41100815, 2025). "Clinically, high EIF4EBP1 expression is associated with poor outcomes in several cancer types." (PMID 38744825, 2024). "Eukaryotic translation initiation factor 4E binding protein 1 (EIF4EBP1) encodes the 4EBP1 protein, a negative regulator of mRNA translation and a substrate of the mechanistic target of rapamycin (mTOR), whose function and relevance in cancer is still under debate." (PMID 35228525, 2022). "Eukaryotic translation initiation factor 4E-binding protein 1 (4E-BP1), encoded by EIF4EBP1 gene, is a key substrate and downstream effector of the mechanistic target of rapamycin complex 1 (mTORC1), implicated in a variety of physiological and pathological processes including aging and cancer." (PMID 36929036, 2023). "Compared with normal breast tissues, PIGR, GPLD1, PLA2G5 and CORO1A were down-regulated in cancer tissues, while EIF4EBP1 and LPCAT1 were significantly up-regulated." (PMID 41450825, 2025). "Further, EIF4EBP1 expression in normal breast epithelial cells and four cancer cells was detected using qRT-PCR." (PMID 41450825, 2025). "To evaluate the potential clinical and functional significance of chr8 gain and EIF4EBP1 expression in other cancer entities besides EwS, we analyzed CNV data from DNA methylation arrays of The Cancer Genome Atlas (TCGA)." (PMID 41100815, 2025). "Myc-regulated protein synthesis is modulated by the mTOR-dependent phosphorylation of eukaryotic translation initiation factor 4E binding protein-1 (4EBP1), which is required for cancer cell survival in Myc-dependent tumours." (PMID 36289203, 2022). "The possible involvement of yet other transcription factors in regulating EIF4EBP1 expression in human cancers remains to be investigated." (PMID 35228525, 2022). "Phosphorylation of Eukaryotic Translation Initiation Factor 4E Binding Protein 1 (EIF4EBP1) has been reported as an important regulator of cancer progression." (PMID 36542699, 2022). "Except for CDKN1B and RELA, the expression levels of CASP7, CDH3, EIF4G1, and EIF4EBP1 were increased significantly in most individual cancer stages compared with normal samples." (PMID 35787690, 2022). "To date, only a few transcription factors have been characterized to bind the EIF4EBP1 promoter and stimulate EIF4EBP1 transcription in normal and cancer cells." (PMID 35228525, 2022). "The EIF4EBP1 protein was moderately expressed in normal tissues and highly expressed in cancer tissues." (PMID 32649310, 2020). "This tool uses gene expression data from Gene Expression Omnibus (GEO), the European Genome-phenome Archive (EGA), and The Cancer Genome Atlas (TCGA).The JetSet probe set for EIF4EBP1 (probe ID: 221539_at) was used for all analyses." (PMID 31122207, 2019). "Blocking VA-induced SG assembly by inactivating eIF4EBP1 or inhibiting eIF2α phosphorylation decreases cancer cell viability and promotes apoptosis." (PMID 27083003, 2016). "The miR-125a and miR-125b mimics repressed EIF4EBP1 mRNA and protein levels in both cancer cell lines." (PMID 26646586, 2016). "Subsequently, total EIF4EBP1 protein was also reported to correlate with worse survival of cancer patients." (PMID 25658620, 2015). "The evidence provided by our study and others indicates that EIF4EBP1 potentially functions as an oncogene in some cancer types." (PMID 25658620, 2015).
cancer (continued). "Notably, the invasion ability of both two cancer cells decreased significantly after infection with si-EIF4EBP1." (PMID 41450825, 2025). "FUT1 targets the fucosylation of CD147, intercellular adhesion molecule 1 (ICAM-1), EGFR, and EPH receptor A2 (EPHA2), consequently converging on the down-regulation of AKT/mTOR/eukaryotic translation initiation factor 4E-binding protein 1 (4EBP1) signaling to enhance cancer stemness." (PMID 40821120, 2025). "Whereas EIF4A1 and EIF4EBP1 are responsible for translation and translation repression, respectively; but with respect to cancer EIF4A1 promotes metastasis, while EIF4EBP1 promotes tumourigenesis when phosphorylated and suppresses tumourigenesis when unphosphorylated." (PMID 37277696, 2023). "The higher transcript levels of the key genes in the Atf4 pathway, such as Trib3 and Asns, which were observed in the ETOH-BKO livers led us to measure 4-EBP1 (EIF4EBP1), as it is a critical ATF4 gene target that is implicated in protein synthesis, metabolic and stress adaptations, and cancer." (PMID 37569418, 2023). "Furthermore, via activation of mTOR (mammalian target of rapamycin) and subsequent phosphorylation of 4EBP1 (eukaryotic translation initiation factor 4E binding protein 1), c-Myc increases protein synthesis in cancers." (PMID 35884563, 2022). "Proteins located downstream of mTORC1, such as eukaryotic translation initiation factor 4E binding protein 1 (4E-BP1) and eukaryotic translation initiation factor 4E (eIF4E), exert significant control over cap-dependent translation, cell growth, and cancer initiation and progression." (PMID 33482765, 2021). "The EIF4EBP1 mRNA level was reported to be up-regulated in some cancer types." (PMID 25658620, 2015). "In the 8p12/11q13 coamplified regions, EIF4EBP1 and RPS6KB2 could be co-targeted and play a synergistic role associated with the development and cancer progression as AKT/MTOR activators." (PMID 24416132, 2014). "Given that mTOR activation isregulated mainly by the IGF-1/AKT pathway, attenuation of AKT activity as observed in ourexperimental cancer cachexia model should further facilitate protein translation inhibitiondue to mTOR inactivation and the consequent hypophosphorylation of EIF4Ebp1." (PMID 21069263, 2011). "Apart from chr8 gains, other possible mechanisms of EIF4EBP1 upregulation, such as direct upregulation driven by differential transcription-factor binding, have been described across cancer entities and also may account for high 4E-BP1 expression levels in individual tumors." (PMID 41100815, 2025). "We further analyzed the potential co-expression of EIF4EBP1 and either ETS1 or MYBL2 at the mRNA level in multiple different cancer types using datasets available in R2 AMC." (PMID 35228525, 2022). "The CCND1 involved in cell cycle progression; TEAD4, a transcription factor in the Hippo signaling pathway; and EIF4EBP1, the translational regulator in PI3K/Akt/mTOR signaling, have been found to be significantly deregulated in several cancers." (PMID 32908901, 2020). "Autophagy-related genes BID, EIF4EBP1, VMP1, SPHK1, and CX3CL1 also play essential roles in other cancers." (PMID 33224313, 2020). "As expected, EIF4EBP1 mRNA and protein are up-regulated in most of HCC cancer tissues compared with their corresponding NCL tissues." (PMID 25658620, 2015). "Overexpression of EIF4EBP1 in cancer is mediated by certain transcription factors, such as MYC, androgen receptor, and the stress regulators ATF4 and HIF-1α, which all bind to and thereby modulate the activity of the EIF4EBP1 promoter." (PMID 35379801, 2022). "Regardless of the cancer types, genes such as ITGA5, SERPINE1, EIF4EBP1 are majorly associated with bad outcomes; while genes such as ALDH2, DBP, FRAT1, PDCD4 are associated with good outcomes." (PMID 35197510, 2022). "Studies show that both EIF4EBP1 and EIF4E are involved in cancer development and progression." (PMID 25658620, 2015).
cancer (continued). "While no studies have specifically focused on EIF4EBP1 or CTPB2 3’ UTR variants in HNSCC, the general role of 3’ UTR variants in cancer suggests they could affect the function of these genes." (PMID 41409254, 2025). "Despite lower overall ERBB2 expression, HER2-HET tumors retained levels of PI3K/ERBB pathway activation equivalent to those in non-HET/pCR cancers, likely due to increased expression of downstream pathway components including MYC and EIF4EBP1." (PMID 38300710, 2024). "Phosphorylation sites on 4EBP1 (gene name EIF4EBP1) or Ribosomal S6 (gene name RPS6), which are known to be downstream of PI3K/mTOR, did not correlate with the responses of our cancer cell panel to the PI3K/mTOR inhibitor PI-103." (PMID 23628362, 2013).
infection (51 papers, 2009 to 2026). The state of being infected such as from the introduction of a foreign agent such as serum, vaccine, antigenic substance or organism. "Infection raises miR-31, which targets eIF4EBP1/2—repressors of cap-dependent translation—biasing protein synthesis toward tumorigenic outputs; high phosphorylated eIF4EBP1 has been linked to poor prognosis." (PMID 41007823, 2025). "Overexpression of EIF4EBP1 reversed this decrease, validating successful infection." (PMID 40486678, 2025). "Moreover, the overexpression of EIF4EBP1 restored its levels, confirming successful infection." (PMID 40486678, 2025).
EIF4EBP1 also shares sentences with these, for which no sentence is quoted: colon carcinoma (30 papers); gastric cancer (19); myeloma (16); lymphoma (15); breast tumors (13); Insulin resistance (11); leukemia (11); non-small cell lung carcinoma (9); Sepsis (9); Hyperglycemia (8); nasopharyngeal carcinoma (8); renal cell carcinoma (8); viral infection (8); endometrial cancer (7); multiple myeloma (7); pituitary tumor (7); astrocytomas (6); Ewing sarcoma (5); lymph node metastasis (5); rhabdomyosarcoma (5); B-cell lymphoma (4); epilepsy (4); head and neck cancer (4); adenocarcinoma (3); Alzheimer disease (3); depression (3); Hyperinsulinemia (3); liposarcoma (3); mantle cell lymphoma (3); prostate tumors (3).
A further 175 diseases each share a sentence with EIF4EBP1 in 3 papers or fewer.